CMIP (c-Maf inducing protein)
Description:
Plays a role in T-cell signaling pathway. Isoform 2 may play a role in T-helper 2 (Th2) signaling pathway and seems to represent the first proximal signaling protein that links T-cell receptor-mediated signal to the activation of c-Maf Th2 specific factor.
Synonyms: TCMIP
Tractability: PROTAC: ubiquitination databases record sites on it; its protein half-life has been measured.
Gene: Protein-coding gene on chromosome 16 (81,444,808 to 81,711,762, forward strand). Ensembl gene ENSG00000153815.
Subcellular location: Nucleus; Cytoplasm
Subcellular location (Human Protein Atlas): Cytosol; Nucleoplasm
Gene Ontology:
Molecular function: protein binding
Cellular component: cytoplasm; cytosol; nucleoplasm; nucleus
Genetic constraint (gnomAD): Loss-of-function variants: 8 observed, 76.42 expected, observed/expected ratio (o/e) 0.1, 90% interval 0.06 to 0.19. The synonymous counts are far from expectation, so gnomAD's model fits this gene poorly and the ratio says little. Missense variants: 775 observed, 898.65 expected, observed/expected ratio (o/e) 0.86, 90% interval 0.81 to 0.92. Synonymous variants: 489 observed, 388.81 expected, observed/expected ratio (o/e) 1.26, 90% interval 1.17 to 1.36.
Homologues: Orthologues: dog CMIP (99% identical), rat Cmip (99% identical), mouse Cmip (98% identical), macaque CMIP (98% identical), pig CMIP (96% identical), chimpanzee CMIP (91% identical), tropical clawed frog CMIP (88% identical), guinea pig CMIP (87% identical), rabbit CMIP (80% identical), zebrafish cmip (75% identical).
Diseases named in the same sentence as CMIP in open-access papers:
CMIP is named in the same sentence as 44 diseases in open-access papers, as found by Europe PMC text mining. Sharing a sentence is not in itself a finding about the gene and the disease. The quoted sentences say what the papers report.
glioma (6 papers, 2017 to 2022). A benign or malignant brain and spinal cord tumor that arises from glial cells (astrocytes, oligodendrocytes, ependymal cells). "High level of CMIP is associated with the more malignant nature of glioma cells and bad prognosis of patients with glioma." (PMID 28744466, 2017). "CMIP has been reported to be associated with gastric cancer and glioma." (PMID 31382519, 2019). "In addition, we conducted association analysis between CMIP expression and clinicopathological parameters in the glioma tissue specimens." (PMID 28744466, 2017). "Therefore, high CMIP expression is associated with poor prognosis in glioma patients." (PMID 28744466, 2017). "Similar conclusions have been reported in a study on glioma cells, where CMIP expression correlates with low relapse-free survival." (PMID 33917766, 2021). "For instance, the transcription factor CMIP was previously shown to be increased in human gastric cancer and glioma tumors, contributing to tumor proliferation and metastasis." (PMID 32183400, 2020). "We studied the localization and expression of CMIP in human glioma cells A172 and U251 (these were chosen because they showed the highest and lowest levels of CMIP expression, resp)." (PMID 28744466, 2017). "In this study, we confirmed that CMIP promotes both proliferation and metastasis of human glioma and demonstrated that CMIP is positively correlated with tumor grade and poor RFS and OS in glioma patients." (PMID 28744466, 2017). "Next, we selected several candidate genes to identify the downstream mechanism of CMIP in human glioma cells." (PMID 28744466, 2017). "Herein we systematically studied the role of CMIP in human glioma both in vitro and in clinical tissues." (PMID 28744466, 2017). "For further study, migration assay and invasion assay in human glioma cells were performed to examine the role of CMIP in cell metastasis." (PMID 28744466, 2017). "The difference of CMIP expression between glioma tissues and adjacent normal tissues was significant (P = 0.018)." (PMID 28744466, 2017). "Our study has confirmed CMIP as an oncogene in human glioma, and this is the first study to report the role of CMIP in human cancers." (PMID 28744466, 2017). "The percentage of tissues with high CMIP expression in high-grade gliomas (grades III-IV) (54.9%) was much higher than that in low-grade glioma (grades I-II) (20.8%) (P = 0.001)." (PMID 28744466, 2017). "Likewise, CMIP expression has been reported in poor prognosis forms of glioma and suggested as a marker differentiating melanoma from nevus." (PMID 33917766, 2021). "Here we have shown that MDM2 is positively regulated by CMIP and may participate in the promoting role of CMIP in human glioma cells." (PMID 28744466, 2017). "CMIP expression was higher in glioma tissues than in normal tissues." (PMID 28744466, 2017). "In conclusion, this study is the first to examine the oncogenic role of CMIP in human glioma." (PMID 28744466, 2017). "Therefore, the oncogenicity of CMIP can be used as a potential target for diagnosis and therapy of human glioma." (PMID 28744466, 2017). "Furthermore, we documented a much higher protein level of CMIP in human glioma tissues than that in normal tissues, and CMIP correlates positively with tumor grade in these glioma tissues." (PMID 28744466, 2017). "Furthermore, high expression of CMIP confers a worse prognosis in glioma patients, including lower RFS and OS." (PMID 28744466, 2017). "Both proliferation and metastasis dramatically decreased after blocking CMIP in glioma cell A172 with high expression of CMIP, whereas, in glioma cell U251 with low CMIP expression, both proliferation and metastasis dramatically increased after pIRESneo3-CMIP transfection." (PMID 28744466, 2017). "While CMIP acts as a tumor promoter in glioma, MDM2 is also reported to be an oncogene." (PMID 28744466, 2017). "CMIP expression was much higher in glioma tissues compared with normal tissues." (PMID 28744466, 2017).
glioma (continued). "Therefore, MDM2 could be involved in the promoting role of CMIP in cell proliferation and metastasis of human glioma cells." (PMID 28744466, 2017). "Our data suggested that CMIP could be used as a new potential therapeutic target for human glioma." (PMID 28744466, 2017). "Therefore, CMIP is oncogenic and could be a potential target for human glioma diagnosis and therapy." (PMID 28744466, 2017). "Therefore, CMIP also promotes metastasis of human glioma cells." (PMID 28744466, 2017). "Therefore, it can be concluded that MDM2 contributes to the oncogenic role of CMIP in human glioma." (PMID 28744466, 2017). "Moreover, CMIP also correlates with low relapse-free survival (RFS) rate and overall survival (OS) rate in glioma patients." (PMID 28744466, 2017). "As such, it can be deduced that CMIP promotes the proliferation of human glioma cells, but no significant change has been detected in the proportion of apoptotic cells." (PMID 28744466, 2017). "Furthermore, we discovered that CMIP upregulates MDM2, which is involved in the promoting role of CMIP in human glioma cells." (PMID 28744466, 2017). "Moreover, CMIP is expressed much higher in glioma tissues compared with normal tissues in our analysis of 99 glioma tissues and 59 normal tissues." (PMID 28744466, 2017). "In glioma tissues, 38 out of 99 cases (38.4%) were CMIP-positive and 61 out of 99 cases (61.6%) were CMIP-negative, whereas, in adjacent normal tissues, 12 out of 59 cases (20.3%) were CMIP-positive and 47 out of 59 cases (79.7%) were CMIP-negative." (PMID 28744466, 2017).
breast carcinoma (4 papers, 2019 to 2021). "In a bioinformatics analysis on data extracted from the Gene Expression Omnibus (GEO) database and the cancer Genome Atlas, aiming to identify prognostic biomarkers of breast cancer, CMIP was included as one of eight hub genes associated with the progression and poor prognosis of breast cancer." (PMID 33917766, 2021). "Furthermore, high CMIP levels were associated with worse prognosis (recurrence-free and overall survival) in gastric and breast cancers and were related with herceptin resistance in HER2-positive gastric cancer cells." (PMID 32183400, 2020). "Furthermore, overexpressed CMIP inversely correlated with breast cancer patients’ survival." (PMID 32514244, 2020).
Type 2 Diabetes (4 papers, 2015 to 2025). "C-Maf Inducing Protein (CMIP) gene polymorphisms were reported to be associated with type 2 diabetes mellitus (T2DM)." (PMID 29597287, 2018). "Many loci associated with adiponectin levels are shared with other insulin resistance traits and risk of type 2 diabetes, including loci near IRS1, LYPAL1, ARL15/FST, VEGFA, CMIP, and PEPD." (PMID 32915782, 2020).
diabetes (3 papers, 2018 to 2023). "It has been reported that the C-Maf inducing protein (Cmip) is associated with metabolic disorders such obesity, diabetes, and NAFLD." (PMID 37190114, 2023). "CMIP primarily acts on the T-cell pathway, which is associated with adiponectin levels, insulin resistance, diabetes, and lipid levels." (PMID 33112407, 2020).
dyslexia (3 papers, 2011 to 2023). A learning disorder characterized by an impairment in processing written words. "We identified association between reading abilities and the DCDC2, KIAA0319, and CMIP genes and have shown that these associations follow different patterns; whereas DCDC2 is associated more specifically with dyslexia, CMIP and KIAA0319 are associated with reading abilities in the normal range." (PMID 21457949, 2011). "They found that there are overlapping expression patterns in human dyslexia-related genes (ROBO1 and KIAA0319, and CNTNAP2 and CMIP) and the expression patterns of these genes in the marmoset brain." (PMID 37760998, 2023).
gastric cancer (3 papers, 2019 to 2021). A primary or metastatic malignant neoplasm involving the stomach. "In gastric cancer cells, CMIP expression is associated with lower survival, while its depletion by RNA interference leads to decreased cell proliferation and migration." (PMID 33917766, 2021). "Conversely, in gastric cancer cells CMIP induces the activity of SOX2, upregulates MDM2 and MAPK transcription." (PMID 33917766, 2021). "In triple negative breast and in gastric cancer cells CMIP is significantly expressed and defined by the authors of these reports as oncogenic." (PMID 33917766, 2021). "Gastric cancer cells resistant to this drug displayed increased CMIP expression, the latter correlated with tumor size and lymph node metastasis by a SOX2-mediated mechanism." (PMID 33917766, 2021).
glomerulopathies (3 papers, 2018 to 2021). "We found CMIP abundance selectively increased in podocytes in class II and class V glomerulopathies, while in proliferative forms (class III and class IV), CMIP was rarely detected." (PMID 30439969, 2018). "CMIP was recently found induced in some glomerular disease but its expression in different lupus nephritis classes has not been investigated." (PMID 30439969, 2018). "In addition, experimental data from several models of podocyte injury suggest that targeting CMIP with specific inhibitors taken up by podocytes may be a promising future therapeutic approach for some glomerular diseases associated with the overproduction of CMIP in podocytes." (PMID 30458703, 2018). "Overexpression of CMIP has been mostly reported in relation to glomerulopathies." (PMID 33917766, 2021). "Interestingly, the coding sequence of CMIP does not seem to be altered in podocyte diseases associated with cancer, in contrast to malignancies— —where multiple mutations have been identified in the CMIP structure, in the absence of related glomerular disease." (PMID 33917766, 2021). "Thus, CMIP induction in lupus nephritis seems restricted to non-proliferative glomerulopathies and may define a specific pattern of podocyte injury." (PMID 30439969, 2018).
Insulin resistance (3 papers, 2020 to 2025). Increased resistance towards insulin, that is, diminished effectiveness of insulin in reducing blood glucose levels. "CMIP (c-Maf-inducing protein) is known to participate in insulin signaling and T-cell activation pathways, and its polymorphisms have been previously associated with insulin resistance and lipid metabolism abnormalities." (PMID 40507058, 2025). "One gene of particular interest is the c-Maf inducing protein (CMIP) gene, which plays a role in T-cell signaling, lipid metabolism, and insulin resistance pathways." (PMID 40507058, 2025).
membranous nephropathy (3 papers, 2018 to 2021). "Accordingly, CMIP upregulation in PBMC and in podocytes is associated with relapses of MCNS, in membranous nephropathy glomeruli and in podocytes in some forms of lupus nephritis." (PMID 33917766, 2021). "CMIP upregulation has been described in renal biopsies from patients with idiopathic MCNS, FSGS and membranous nephropathy, whereas CMIP is not generally expressed in inflammatory and proliferative glomerular diseases, such as IgA nephropathy or active lupus nephritis." (PMID 30458703, 2018).
Obesity (3 papers, 2015 to 2023). Accumulation of substantial excess body fat. "As an intron variant of CMIP, rs2925979 may also have the potential of being associated with sex hormones in obesity, and studies are needed to verify this hypothesis." (PMID 29597287, 2018). "The opposite associations of rs2925979_T allele with T2DM and obesity-related phenotypes suggest that CMIP may exert independent pleiotropic effects on T2DM and obesity-related phenotypes in females." (PMID 29597287, 2018). "In summary, CMIP rs2925979_T allele was associated with an increasing risk of T2DM and with decreasing levels of most obesity-related phenotypes in females, exerting pleiotropic genetic effects." (PMID 29597287, 2018). "In this paper, we analyzed data of 1576 families ascertained from a Chinese population to examine the association of the CMIP locus with T2DM and with a comprehensive set of obesity-related phenotypes." (PMID 29597287, 2018). "CMIP (C-Maf-Inducing Protein) gene is a protein-coding gene located on 16q23.2-q23.3 and involved in multiple signaling pathways related to obesity and T2DM, such as nuclear factor-κB (NF-κB) signaling pathway and T-helper 2 (Th2) signaling pathway." (PMID 29597287, 2018). "We analyzed the association of CMIP rs2925979 with T2DM and a comprehensive set of obesity-related phenotypes in 1576 families ascertained from a Chinese population." (PMID 29597287, 2018). "Whether the association between CMIP and T2DM is mediated via obesity-related phenotypes is still unclear." (PMID 29597287, 2018). "Sex genetic architecture may influence the genetic effects of CMIP rs2925979 polymorphisms on T2DM and obesity." (PMID 29597287, 2018).
idiopathic nephrotic syndrome (2 papers, 2021). Nephrotic syndrome for which no cause has been identified. "The C-Maf-Inducing protein (CMIP) was first described as overexpressed in T cell subpopulations of idiopathic nephrotic syndrome (INS) patients." (PMID 33917766, 2021).
IgA nephropathy (2 papers, 2018 to 2020). "The relationship between serum lipid profiles and related clinicopathologic features of IgA nephropathy (IgAN) and c-Maf-inducing protein (CMIP) gene polymorphisms is unclear." (PMID 33112407, 2020).
language disorder (2 papers, 2010 to 2011). A category of disorders characterized by an impairment in the development of an individual's language capabilities, which is in contrast to his/her non-verbal intellect. "We provide further support for the role of KIAA0319 and DCDC2 in contributing to reading abilities and novel evidence that the language-disorder candidate gene CMIP is also implicated in reading processes." (PMID 21457949, 2011). "We did not detect any pleiotropic effect, which could partly explain the comorbidity between RD and SLI, although CMIP, selected as a candidate for language disorder, showed association with reading." (PMID 21457949, 2011).
lupus nephritis (2 papers, 2018). Glomerulonephritis in the context of systemic lupus erythematosus. "We report for the first time the expression of CMIP in lupus nephritis." (PMID 30439969, 2018). "However, one patient with class II lupus nephritis and overexpressing CMIP in podocytes died of active neurolupus." (PMID 30439969, 2018). "To assess whether CMIP gene was actively transcribed in lupus nephritis and, if so, if its induction was restricted to a particular pattern of glomerular injury, we analyzed the transcript level by quantitative PCR from laser microdissected glomeruli." (PMID 30439969, 2018). "In the present work, we aimed to study whether CMIP could be expressed in lupus nephritis, and to determine whether its expression could be correlated with a particular pattern of lupus nephritis." (PMID 30439969, 2018). "Our results suggest that induction of CMIP in lupus nephritis appears to be limited to non-proliferative forms and may define a specific pattern of podocyte injury." (PMID 30439969, 2018). "Collectively, these data suggest that CMIP is strongly induced in podocyte diseases in the context of lupus glomerulopathies but its expression was restricted to non-inflammatory classes such as lupus nephritis classes II and V." (PMID 30439969, 2018).
autism (1 paper, 2013). Persistent deficits in social interaction and communication and interaction as well as a markedly restricted repertoire of activity and interest as well as repetitive patterns of behavior. "For example, haploinsufficiency of Shank3, CMIP, FOXP2 and Tsc2 has already been linked to the etiology and phenotypic characteristics of autism." (PMID 23451085, 2013).
colitis (1 paper, 2021). Inflammation of the colon. "Other findings include that of CMIP peptides bound to MHC class II molecules isolated from lymph nodes in a mouse model of colitis, which suggests that CMIP could be an autoantigen in autoimmune conditions." (PMID 33917766, 2021).
dyslipidaemia (1 paper, 2020). "The relationships between dyslipidaemia, clinicopathologic features, and CMIP single-nucleotide polymorphisms (SNPs) and their haplotypes have rarely been reported." (PMID 33112407, 2020). "The present study was designed to investigate the effects of CMIP SNPs (CMIP rs2925979 and CMIP rs16955379) in patients with IgAN and dyslipidaemia and to explore the clinicopathologic features associated with CMIP SNPs in patients with IgAN." (PMID 33112407, 2020). "CMIP was not only a susceptibility gene for dyslipidaemia in patients with IgAN but also affected renal progression and prognosis in these patients." (PMID 33112407, 2020). "CMIP SNPs and their haplotypes are closely associated with dyslipidaemia and are also related to clinical features and pathological damage in patients with IgAN." (PMID 33112407, 2020). "CMIP SNPs and their haplotypes are closely correlated with the occurrence of dyslipidaemia and clinicopathologic damage in IgAN patients." (PMID 33112407, 2020). "A significant difference was observed between the dyslipidaemia and non-dyslipidaemia groups in CMIP rs16955379 CC, CT, and TT genotype frequencies (P<0.05)." (PMID 33112407, 2020). "The combined effects of CMIP SNPs (CMIP rs2925979 and CMIP rs16955379) between dyslipidaemia and non-dyslipidaemia groups in patients with IgAN were examined using haplotype analysis." (PMID 33112407, 2020). "The frequencies of the four CMIP SNP haplotypes differed between dyslipidaemia and non-dyslipidaemia groups in IgAN (P<0.05, for all above)." (PMID 33112407, 2020).
glomerulosclerosis (1 paper, 2021). A hardening of the kidney glomerulus caused by scarring of the blood vessels. "In the absence of response to therapy, the persistent expression of CMIP may contribute to the development of podocyte damages and, belatedly, of glomerulosclerosis." (PMID 34323419, 2021).
HIV-associated nephropathy (1 paper, 2018). Renal disease in human immunodeficiency virus (HIV)-infected patients. "We evaluated HIV infection by in situ hybridization and CMIP expression by immunochemistry on kidney biopsies and compared it to HIV-associated nephropathy (HIVAN) and idiopathic MCNS." (PMID 30458703, 2018).